SNORA48 (small nucleolar RNA, H/ACA box 48)
Synonyms: ACA48; SNORA48A
Gene: Small nucleolar RNA gene on chromosome 17 (7,574,713 to 7,574,847, forward strand). Ensembl gene ENSG00000209582.
Gene Ontology:
Biological process: RNA processing
Cellular component: nucleolus
Homologues: Orthologues: chimpanzee SNORA48 (100% identical), macaque SNORA48 (97% identical), rabbit SNORA48 (84% identical). Paralogues in human: SNORA48B (92% identical).
Diseases named in the same sentence as SNORA48 in open-access papers:
SNORA48 is named in the same sentence as 5 diseases in open-access papers, as found by Europe PMC text mining. Sharing a sentence is not in itself a finding about the gene and the disease. The quoted sentences say what the papers report.
leiomyoma (1 paper, 2024). A well-circumscribed benign smooth muscle neoplasm characterized by the presence of spindle cells with cigar-shaped nuclei, interlacing fascicles, and a whorled pattern. "SNORA48 and SNORD10 (coding for small nucleolar RNAs) have not yet been described in leiomyomas, however were upregulated in both our cases." (PMID 37466765, 2024).
meningioma (1 paper, 2019). A generally slow growing tumor attached to the dura mater. "In our study, the higher levels of SNORA46 and SNORA48 found in low-grade meningiomas compared to higher-grade tumors point towards their role as cancer or tumor progression suppressors." (PMID 31039818, 2019). "Among the genes that we have identified as being differentially expressed between grade I and grade II-III tumors are GREM2, SNORA46, and SNORA48, found at higher levels in low grade meningiomas than in higher grade tumors." (PMID 31039818, 2019). "GREM2, SNORA46, and SNORA48 were each expressed at significantly higher levels in grade I meningiomas than grade II and III (p = 0.047, p = 0.017, and p = 0.038, respectively; one-tailed t-test)." (PMID 31039818, 2019). "Among the numerous genes differentially expressed across meningioma grades, we identified GREM2, a regulator of the BMP pathway, and the snoRNAs, SNORA46 and SNORA48, as being significantly reduced in meningioma progression by RNA-seq analysis." (PMID 31039818, 2019). "When analyzing these genes’ expression across each meningioma grade, we observed how GREM2, SNORA46, and SNORA48 were expressed at significantly higher levels in I NP when compared to I P, secondary or de novo grade II, and grade III." (PMID 31039818, 2019).
tumor (2 papers, 2019 to 2024). "Significant change of expression, reaching 10- to 58-fold change between uterine lesion compared to non-tumor counterpart, was observed in CAPN6, CD24, HMGA1, PLAG1, SNORA48, and SNORD10 (upregulation) and DKK3 and STK26 (downregulation)." (PMID 37466765, 2024).
SNORA48 also shares sentences with these, for which no sentence is quoted: cancer (1 paper); infection (1).